LRP1 (LDL receptor related protein 1)
Diseases named in the same sentence as LRP1 in open-access papers (continued):
Sharing a sentence is not in itself a finding about the gene and the disease.
Insulin resistance (19 papers, 2017 to 2025). Increased resistance towards insulin, that is, diminished effectiveness of insulin in reducing blood glucose levels. "In fact, a recent survey revealed that LRP1 polymorphism is the top gene variation among 1,000 candidate gene variations in influencing fasting insulin and C-peptide levels and insulin resistance in patients with metabolic syndrome." (PMID 33500241, 2021). "In line with this, we found an inverse correlation between sLRP-1 levels and TyG, a marker of insulin resistance suggestive of the potential contribution of the decreased LRP-1 concentration to OSA-associated insulin resistance." (PMID 33916750, 2021). "Previous studies have shown that hepatic LRP1 deficiency exacerbates diet-induced steatohepatitis and insulin resistance via mechanisms related to increased lysosome and mitochondria permeability and dysfunction." (PMID 33548224, 2021). "Since there is a tight relationship between LRP1 levels and IR signaling, it is possible that, in sleep-restricted rats, the decrease in LRP1 is associated with altered IR signaling, resulting in insulin resistance." (PMID 34539357, 2021). "A recent study examining 450 participants in the LIPGENE cohort demonstrated that rs4759277 within the LRP1 gene is the top single nucleotide polymorphism (SNP) associated with fasting insulin, C-peptide, and insulin resistance." (PMID 30524198, 2018). "Additional experiments were performed with primary hepatocytes isolated from wild-type and LRP1 NPxY mutant mice to determine whether the LRP1 NPxY mutation affects hepatic insulin resistance." (PMID 33500241, 2021). "In particular, the LRP1 NPxY mutant mice are similar to wild-type mice in response to HF feeding, while HF diet-fed hLrp1−/− mice are predisposed to metabolic disease with more robust insulin resistance, dyslipidemia, and hepatosteatosis compared with HF diet-fed wild-type mice." (PMID 33500241, 2021). "In genome-wide association studies (GWAS), it was also found that the LRP1 single nucleotide polymorphism (SNP), rs4759277, is strongly linked to phenotypic alterations of the carbohydrate metabolism, such as fasting insulin, C-peptide and homeostasis assessment of insulin resistance." (PMID 29914093, 2018). "Finally, it was found that mice LRP1 deficiency in cardiomyocytes resulted in a reduced aggLDL uptake, thereby preventing left ventricular dysfunction, esterified cholesterol accumulation and insulin resistance." (PMID 29914093, 2018). "A different study reported that LRP1 protects against hepatic insulin resistance and hepatic steatosis." (PMID 37156995, 2023). "Insulin resistance impairs LRP1 translocation, contributing to its functional impairment in clearing Aβ." (PMID 37377968, 2023). "An impaired hepatic LRP1 translocation can contribute to postprandial hyperlipidemia in insulin resistance." (PMID 37762244, 2023). "Insulin resistance in the liver can impair the translocation of LRP1 from intracellular vesicles to the hepatocyte plasma membrane, and this then leads to a reduced clearance of TRLs." (PMID 35761281, 2022). "The cardiometabolic benefits of macrophage LRP1 signaling are counterbalanced by its enhancement of Wnt signaling that leads to hepatic inflammation and insulin resistance." (PMID 33548224, 2021). "Our studies also appear to contradict the protective effect of hepatic LRP1 against hepatic insulin resistance and steatosis and neuronal LRP1 in preventing glucose intolerance in the brain." (PMID 30524198, 2018). "In glucose homeostasis, LRP1 has a regulatory action on the insulin receptor (IR) and GLUT4 activation, which has been strongly associated with insulin resistance developed during MetS." (PMID 29914093, 2018). "Collectively, our results suggest that LRP1 expression in macrophages promotes hepatic inflammation and the development of glucose intolerance and insulin resistance by modulating Wnt signaling." (PMID 30524198, 2018).
Insulin resistance (continued). "A previous study successfully demonstrated that insulin resistance suppresses LRP1 expression, which may further compromise insulin signaling and cholesterol metabolism in neurons." (PMID 37342358, 2023). "Hence, the LRP1 NPxY mutant mice are similar to wild-type mice in HF diet-induced hypercholesterolemia, hyperglycemia, insulin resistance, and hepatosteatosis." (PMID 33500241, 2021). "However, despite these improvements, the LRP1 NPxY mutant mice are equally susceptible to HFHC diet-induced hyperglycemia, hyperinsulinemia, and insulin resistance." (PMID 33500241, 2021). "In humans, apoA5 could be internalized by human adipocytes primarily via binding to LRP1, and the uptake of apoA5 was attenuated in obese adipose tissues and in cultured adipocytes with hypertrophy or insulin resistance." (PMID 30053818, 2018). "It has been reported that LRP1 depletion in GSVs substantially affects the sorting of GLUT4 to the plasma membrane in 3T3-L1 adipocytes and adipose-specific LRP1 knock-out mice, with this event involving the insulin resistance and increased blood glucose levels occurring during MetS and T2DM." (PMID 29914093, 2018). "Thus, mutation and dysfunction of the distal NPxY motif in LRP1 is not sufficient to explain the relationship between LRP1 polymorphism and insulin resistance in patients with metabolic syndrome." (PMID 33500241, 2021). "Insulin resistance induced by sleep restriction could also contribute to Aβ accumulation in the brain by the regulation of LRP1 and RAGE function, driving neuroinflammation, neurodegeneration, and cognitive impairment, all factors that contribute to AD development." (PMID 34539357, 2021). "It has been shown that liver dysfunction and hepatic insulin resistance impedes clearance of circulation amyloid β through a reduction in hepatic LRP-1 expression and LRP-1 translocation to the hepatocyte membrane." (PMID 33572481, 2021). "Nevertheless, insulin signaling is impaired in LRP1 NPxY mutant hepatocytes and this mutation does not exacerbate or protect against HFHC diet-induced hyperglycemia, hyperinsulinemia, and insulin resistance." (PMID 33500241, 2021). "Thus, LRP1‐ induced BBB integrity damage might represent the possible mechanism linking APOE genotype and insulin resistance." (PMID 39992249, 2025). "However, unlike the liver-specific LRP1 knockout mice, the impairment of hepatic insulin signaling did not further exacerbate diet-induced hyperglycemia, hyperinsulinemia, and insulin resistance." (PMID 33500241, 2021).
hepatocellular carcinoma (17 papers, 2012 to 2025). A malignant tumor that arises from hepatocytes. "Similar to LYVE1, downregulation of LRP1 was also associated with invasiveness and poor prognosis in hepatocellular carcinoma." (PMID 40551123, 2025). "The loss of Low-density lipoprotein receptor-related protein 1 (LRP1) has been shown to promote hepatocellular carcinoma progression through UFL1-mediated activation of NF-κB signaling." (PMID 41179291, 2025). "Another study showed that low LRP1 levels are also associated with poor prognosis of hepatocellular carcinoma, a pathological condition that is often associated with liver cirrhosis caused by hepatitis virus, alcoholic fatty liver, and non-alcoholic fatty liver." (PMID 33500241, 2021). "Furthermore, a recent study has demonstrated that high expression of LRP1 is associated with a low metastatic potential of hepatocellular carcinoma (HCC)." (PMID 26738504, 2016). "In hepatoma cells, Wnt co-receptors LRP-5/6 and LRP-1, implicated in cell survival and invasiveness, were upregulated by SerpinB3." (PMID 37372056, 2023). "In hepatocellular carcinoma and Wills tumor cells, the diminished expression of LRP1 in tumor cells correlated with increased levels of MMP9, probably due to loss of LRP1-mediated endocytosis." (PMID 29507659, 2018). "Immunofluorescence studies indicate the LRP1-dependent trapping of apoE in EEA1-positive endosomes in human hepatoma cells." (PMID 22238606, 2012). "The aim of this study was to elucidate the expression and mechanism of LRP1 in hepatocellular carcinoma (HCC)." (PMID 22427881, 2012). "To clarify the cellular localization of LRP1 in liver cells, we performed co-localization studies in human HuH7 hepatoma cells." (PMID 22238606, 2012). "Similarly, some studies have indicated that Rosiglitazone, a well-known compound with antidiabetic properties, modulates LRP1 expression in a hepatocellular carcinoma cell line." (PMID 30523204, 2019). "Indeed, several studies have reported that low LRP1 expression was closely related to advanced tumor stages and poor survival in several solid tumors, such as hepatocellular carcinoma, lung adenocarcinoma melanoma and Wilms tumors." (PMID 29507659, 2018). "In prostate cancer, LRP1 expression is observed mostly in tumors with a high Gleason grade, which are the most progressive tumors; however, in hepatocellular carcinoma, a reduction in LRP1 expression may correlate with tumor progression." (PMID 29138479, 2017). "Finally, we evaluated the in vivo effects of LRP1 expression in hepatoma xenografts." (PMID 39405202, 2024). "Low‐density lipoprotein receptor‐related protein‐1 (LRP1) is thought to be correlated with hepatocellular carcinoma (HCC) invasion and metastasis." (PMID 39405202, 2024). "Supporting that, an increased expression of LRP1 results in a low metastatic potential of hepatocellular carcinoma (HCC)." (PMID 37020553, 2023). "Hence, the relationship between LRP1 levels and hepatocellular carcinoma may be related to aberrant lipid metabolism in the liver." (PMID 33500241, 2021). "While no LRP‐1 (TβR‐V) is detected in hepatoma in human patients, it is present in the normal parenchymal tissue surrounding the hepatomas." (PMID 34485840, 2021).
colorectal cancer (16 papers, 2020 to 2026). A primary or metastatic malignant neoplasm that affects the colon or rectum. "Previous studies have shown that LRP1 expression is significantly lower in colon adenocarcinoma cells than in colon mucosa and stromal cells and is associated with worse colorectal cancer outcomes." (PMID 36973740, 2023). "Also, LRP1 is highly expressed in radioresistant colorectal cancer and higher expression of LRP1 is associated with poor clinical outcomes." (PMID 40835598, 2025). "Furthermore, APOE has been shown to enhance the migration and invasion capabilities of colorectal cancer cells by interacting with low‐density lipoprotein receptor‐associated protein 1 (LRP1)." (PMID 40437660, 2025). "In colorectal cancer, low-density lipoprotein receptor-related protein 1 (LRP-1) regulates DDR1 expression via endocytosis, promoting cell cycle progression into the S-phase and enhancing tumor proliferation." (PMID 40563472, 2025). "Our results demonstrated that α-1,2 fucosylation was crucial for the inhibition of EMT and invasion by LRP1 in colorectal cancer cells." (PMID 36973740, 2023). "FUT2-induced α-1,2 fucosylation impacts the ability of low-density lipoprotein receptor-related protein 1(LRP1) to suppress colorectal cancer invasion." (PMID 36973740, 2023). "In this regard, Lee and collaborators (2020) reported the identification of low-density lipoprotein receptor-related protein-1 (LRP1) as a biomarker of radio-resistant colorectal cancer cells in a model of a patient-derived xenograft (PDX)." (PMID 35631681, 2022). "Additionally, Hsp90α induces colorectal cancer cell invasion through CD91/LRP-1 and NF-kappa B-mediated expression of integrin αV." (PMID 38727789, 2024). "Our study demonstrated that FUT2 induces α-1,2 fucosylation and inhibits EMT and metastasis of colorectal cancer through LRP1 fucosylation, suggesting that FUT2 may serve as a therapeutic target for colorectal cancer." (PMID 36973740, 2023). "Our study demonstrated that FUT2 induces α-1,2 fucosylation and inhibits the EMT and metastasis of colorectal cancer through LRP1 fucosylation, suggesting that FUT2 may serve as a therapeutic target for colorectal cancer." (PMID 36973740, 2023). "Therefore, LRP1 expression may be a point for interventions to promote efficacy of anticancer drugs by allowing their more efficient uptake in lung adenocarcinoma and colorectal carcinoma." (PMID 34281263, 2021). "Besides, Presenilin1 also cleaves another type 1 transmembrane protein such as Alcadein α, Deleted in colorectal cancer (DCC), LDL receptor family (LRP1 and LRP8), p75-neurotrophin receptor (p75NTR), NOTCH receptor." (PMID 34781973, 2021).
Hypercholesterolemia (16 papers, 2012 to 2025). An increased concentration of cholesterol in the blood. "In contrast, when the animals were fed an HFHC diet, the LRP1 NPxY mutation prevents hypercholesterolemia, reduces adipose and brain tissue inflammation, and limits steatotic liver progression to steatohepatitis." (PMID 33500241, 2021). "In conclusion, α2M* by its agonist action on LRP1, counteracts the deleterious effects of aggLDL in cardiomyocytes, which may have therapeutic implications in cardiovascular diseases associated with hypercholesterolemia." (PMID 34203120, 2021). "However, LRP1 NPxY mutation prevents HFHC diet-induced hypercholesterolemia, reduces adipose tissue and brain inflammation, and limits liver progression to steatohepatitis." (PMID 33500241, 2021). "LRP1 is upregulated by cardiovascular risk factors such as hypercholesterolemia and hypertension." (PMID 22828168, 2012). "Therefore, cardiovascular risk factor such as hypercholesterolemia or hypertension likely modulate LRP1 expression in the myocardium, as previously reported by our group in the vascular wall." (PMID 22873206, 2012). "Hypercholesterolemia decreased LRP1 expression, which would decrease Abeta efflux across the BBB, and increased RAGE expression, which would increase Abeta influx through the BBB, in cerebral endothelial cells." (PMID 36845656, 2023). "Taken together, these results suggest that NPxY motif mutation in LRP1 abrogates cholesterol-induced LXR activation, thereby decreasing PCSK9 expression to suppress cholesterol-induced hypercholesterolemia." (PMID 33500241, 2021). "The importance of circulating soluble LRP1 (sLRP1) protein level as a potential biomarker of hypercholesterolemia was indicated by the higher sLRP1 levels in patients with severe hypercholesterolemia compared to those with moderate elevation or normal levels of serum cholesterol." (PMID 28577571, 2017). "Hypercholesterolemia increases Abeta production by increasing BACE1 and RAGE levels, and decreasing IDE (Insulin Degrading Enzyme) and LRP1 levels." (PMID 36845656, 2023). "In our study, hypermethylation of promoters of key genes regulating cholesterol metabolism such as PCSK9, LRP1, ABCG1, ANGPTL4, SREBF1 and NR1H2, were found in obese patients with hypercholesterolemia." (PMID 33028190, 2020). "LRP1 is also upregulated by extracellular matrix-aggregated LDL in cultured human vascular smooth muscle cells and by hypercholesterolemia in the porcine vascular wall." (PMID 22873206, 2012). "The mechanism by which mutation of the distal NPxY motif in LRP1 alleviates dietary cholesterol-induced hypercholesterolemia was explored by comparing VLDL synthesis/secretion and plasma lipid clearance between wild-type and LRP1 NPxY mutant mice after feeding the HFHC diet for 16 weeks." (PMID 33500241, 2021).
ischemic stroke (16 papers, 2017 to 2026). A stroke disorder caused by obstruction of blood flow to the brain, due to thrombotic (local blood clot formation) or embolic (due to a blood clot or other material traveling from another site) event. "Ischemic stroke results in dysfunction of mitochondrial oxidative phosphorylation and stress, with low-density lipoprotein receptor-related protein-1 (LRP1) implicated in this condition." (PMID 39325940, 2024). "There are some possible mechanisms such as the modulation by LRP1 (encoding low density lipoprotein receptor-related protein 1) of the axonal regeneration in ischemic stroke through the binding of uPA to uPAR in the periphery of growth cones of injured axons." (PMID 29342922, 2018). "Mac-1 is expressed on microglia and has been shown to associate with both tPA and LRP1 on leukocytes, and like tPA-deficient mice, Mac-1−/− mice are protected from ischemic stroke (Online Resource 1)." (PMID 28725968, 2017). "In a mouse model of ischemic stroke, the inhibition of LRP1 in astrocytes impeded the transfer of mitochondria to neurons, thereby exacerbating ischemic stroke." (PMID 39683818, 2024). "Altogether, our findings suggest that LCN2/LRP1 regulates astrocyte-mediated myelin phagocytosis in a mouse model of ischemic stroke." (PMID 35241660, 2022). "We developed and evaluated the therapeutic potential of a novel delivery vehicle which encapsulated carnosine in lipoprotein receptor related protein-1 (LRP-1)-targeted functionalized polymersomes in experimental ischemic stroke." (PMID 31959846, 2020). "Using both a cell-based PDGFRα activation assay and a photothrombotic model of ischemic stroke, we show that both Mac-1 and LRP1 are required for efficient activation of PDGF-CC by tPA and the subsequent phosphorylation of the PDGFRα." (PMID 28725968, 2017). "It is noteworthy that LRP‐1 plays a complex role in ischemic stroke." (PMID 40116141, 2025). "Following ischemic stroke, a significant increase in tissue plasminogen activator-dependent cerebrovascular permeability occurs via signaling through the activated PDGFRα pathway and LRP1 pathway." (PMID 30186167, 2018). "Several studies suggested that LRP‐1 is one of the targets leading to BBB dysfunction and demyelination after ischemic stroke." (PMID 40116141, 2025). "Lrp1 expression is increased upon ischemic stroke, and treatment with RAP or antibodies against Lrp1 decreases the degree of tissue edema after middle cerebral artery occlusion." (PMID 30931303, 2019). "This could provide further clarification regarding the inhibitory effect of LRP1 in astrocytes on lactate production and the reduction in ADP-ribosylation factor 1 (ARF1) lactylation, as well as the promotion of astrocyte mitochondrial transfer to neurons and the alleviation of ischemic stroke." (PMID 39683818, 2024).
lung carcinoma (15 papers, 2014 to 2025). "Exosomal components, including proteins such as EGFR, LRP1, and LG3BP, as well as RNAs present in the serum and urine of lung cancer patients, have been associated with the stage and metastasis of the disease." (PMID 41573685, 2025). "The contrary functions of EEF2 and LRP1 in lung cancer, along with DST shared expression with EEF2, are evident." (PMID 38389572, 2024). "Studies reported that exosomal proteins found in patient serum and urine, such as LRP1, EGFR and LG3BP, have been associated to lung cancer stage and metastasis." (PMID 37400751, 2023). "To further validate our RNA-Seq results, we utilized a different human lung cancer cell line H1838 and examined the expression level of COL1A2, LRP1, and HSP90B1, three representative genes up-regulated in our RNA-Seq analysis." (PMID 37487081, 2023).